CD163 (CD163 molecule)
Diseases named in the same sentence as CD163 in open-access papers (continued):
Sharing a sentence is not in itself a finding about the gene and the disease.
autoimmune disease (24 papers, 2007 to 2025). A disorder resulting from loss of function or tissue destruction of an organ or multiple organs, arising from humoral or cellular immune responses of the individual to their own tissue constituents. "Urine CD163, as a noninvasive biomarker, has been found to be associated with renal involvement in autoimmune diseases and showed higher sensitivity and specificity than the serum CD163 levels." (PMID 33997033, 2021). "Soluble CD163 serves as an activating marker of CD163+ M2‐polarized macrophages, which play a role in various autoimmune disorders." (PMID 39822761, 2025). "Research indicates that CD163 can serve as a biomarker for various diseases, including infections, autoimmune diseases, cancers, and nervous system abnormalities." (PMID 41036279, 2025). "For example, it has been shown that CD163+ activated tissue macrophages are increased in several autoimmune diseases such as BP, pemphigus vulgaris, and systemic sclerosis." (PMID 38116004, 2023). "Serum CD163 concentrations in peripheral blood reflect the disease severity in autoimmune diseases such as rheumatoid arthritis, systemic sclerosis, and idiopathic inflammatory myositis." (PMID 35911758, 2022). "The level of soluble CD163 (sCD163) has been suggested as an indicator of autoimmune diseases such as SLE." (PMID 35935949, 2022). "Significantly reduced amounts of CD163+ macrophages were found in Lyme borreliosis patients grouped according to the concurrent manifestation of autoimmune diseases." (PMID 31366164, 2019). "CXCL5 is a biomarker of Th17-mediated autoimmune diseases, such as multiple sclerosis, rheumatoid arthritis, and pemphigus vulgaris, and sCD163 is an activation marker for CD163+ TAMs that appears in the serum as a result of proteolytic shedding." (PMID 29050354, 2017). "In this respect, increased numbers of CD14-expressing monocytes, CD68 or CD163-expressing macrophages, CD1c or CD11c-expressing myeloid dendritic cells have been documented in different autoimmune diseases." (PMID 24740301, 2014). "We have previously shown in human patients with acute inflammatory and autoimmune diseases that comparable immunosuppressive glucocorticoid treatment protocols stimulate strong CD163 expression and Hb:Hp endocytosis capacity in peripheral blood monocytes." (PMID 25346694, 2014). "Increased expression of CD163 has been also seen in skin macrophages and peripheral blood monocytes of patients with systemic sclerosis, an autoimmune disease characterized by local inflammatory infiltrates and widespread fibrosis." (PMID 23922818, 2013). "An increase of CD163-positive cells in colonic mucosa seems to play a role in mediating autoimmune diseases, such as Crohn's disease." (PMID 18047662, 2007). "CD163 is increased on myeloid cells near neurodegenerative pathology, including PD, while soluble CD163 correlates with exacerbation of inflammation and worsening disease outcomes in neurodegenerative, inflammatory, and autoimmune diseases." (PMID 40771809, 2025). "CD163, known as the haptoglobin‐hemoglobin receptor, is a 130 kDa membrane protein expressed exclusively on monocytes or macrophages that binds and scavenges oxidized and pro‐inflammatory hemoglobin in autoimmune diseases." (PMID 38651547, 2024). "Furthermore, there were a certain number of studies that investigated the links between CD163 with the occurrence and development of autoimmune diseases." (PMID 33997033, 2021). "Notably, CXCL5 is a biomarker of T helper 17 cell-mediated autoimmune diseases such as multiple sclerosis, rheumatoid arthritis, and pemphigus vulgaris; and soluble CD163 (sCD163) is a TAM marker that appears in the serum as a result of proteolytic shedding." (PMID 29643991, 2018).
autoimmune disease (continued). "Soluble CD163 is thought to be involved in the resolution of inflammation by mechanisms that are not yet fully understood, but include inhibition of T cell activation, and is increased in autoimmune disorders, hematological malignancies, malaria, and bacterial, but not viral meningitis." (PMID 21625498, 2011). "The scavenger receptor CD163 has been investigated as a potential marker of inflammation in infectious diseases such as meningitis, as well as in autoimmune diseases driven by activated macrophages, and so may have potential as a monitoring tool in management of HIV-1 disease." (PMID 21625498, 2011). "A combination of four different proteins: BDNF (Brain Derived Neurotrophic Factor), I-TAC/CXCL11, soluble (s) CD163 and Fractalkine/CX3CL1 was identified as a pSS protein signature as it could discern pSS from other autoimmune diseases." (PMID 35892673, 2022). "Given that endometriosis is an autoimmune disease, we speculate that the macrophages treated with serum of patients with endometriosis may simultaneously express CD86 and CD163, representing a special type of M2 macrophages." (PMID 30276219, 2018). "It is the case, for example, of the presence of the M2 markers CD163 or soluble (s)CD163 that showed to be higher in presence of several organ involvements, like in ILD and pulmonary arterial hypertension (PAH), in SSc and other autoimmune diseases, like polymyositis and dermatomyositis." (PMID 30249259, 2018).
lung adenocarcinoma (24 papers, 2018 to 2026). A carcinoma that arises from the lung and is characterized by the presence of malignant glandular epithelial cells. "Tumor cell population can also express CD163, and detection of high number of CD163+ tumor cells is associated with poor prognosis and shorter survival in lung adenocarcinoma." (PMID 38740647, 2024). "Previous work has linked stromal FAP to immune cell infiltration, including CD8+ T cells and CD163+ macrophages, in MRI‐visible prostate tumours, lung adenocarcinoma, and in clear cell renal cell carcinoma." (PMID 41410015, 2026). "As expected, lung adenocarcinoma was massively infiltrated by CD163-positive macrophages (large cells with abundant, vacuolated cytoplasm and a round, regular nucleus containing a small nucleolus)." (PMID 39424955, 2024). "Further, CD68+CD163+ or CD68+CD206+ markers were used to identify M2-polarized TAMs in lung adenocarcinoma." (PMID 36077342, 2022). "To investigate if reduced CD68+/CD163+ TAMs within in situ regions has an impact on lung adenocarcinoma development, we first assessed the link between statin use and pathological tumor staging." (PMID 32190817, 2020). "High expression levels of CD163 in macrophages relate with high mortality in malignancies, including lung adenocarcinoma." (PMID 30065206, 2018). "For example, in lung adenocarcinoma in mice, it was demonstrated that the bacteria Diaphorobacter nitroreducens, when combined with oxaliplatin, increased the number of CD163- and CD68-positive macrophages while reducing Treg cells (CD4 FOXP3), thus slowing tumor progression." (PMID 40075568, 2025). "For example, IBC should be preferred for patients with low PD1+CD8+ T‐cell or high CD163+ TAM infiltration in the TME because low PD1+CD8+ T‐cell and high CD163+ TAM represent two major immunosuppressive phenotypes in HER2‐altered lung adenocarcinoma." (PMID 40960008, 2025). "Direct contact with lung adenocarcinoma cells promotes monocytes phenotype skewing from M1 to the M2‐like/TAM state, as evidenced by the increased levels of CD206 and CD163 markers gene expression in 3D tumor spheroids of A549 and NCI‐H460 cells." (PMID 35658112, 2024). "We used flow cytometry to validate lung adenocarcinoma cells, normal epithelial cells, and macrophages with cell markers (EPCAM, FOLR1, and CD163)." (PMID 36249427, 2022). "Hence, we predicted that during radiotherapy, alterations of the percentages of MDSCs are more sensitive in lung adenocarcinoma patients, while CD68+CD163+M2-like macrophages are more specific for lung squamous carcinoma patients." (PMID 35928634, 2022). "This was further validated in human non-cancerous and lung adenocarcinoma biopsies where lung adenocarcinoma samples showed higher expression of CD163 and CD206 as compared to the non-cancerous samples." (PMID 35837091, 2022). "We also investigated whether there was a correlation between SPP1 gene expression and various macrophage markers, such as CD204, Iba-1, CD68, CD163, and CD163L1, in lung adenocarcinoma tissues." (PMID 36139536, 2022). "We next investigated whether there was an association between statin use and TAM number and polarity by quantitation of CD68/CD163 staining in statin users and nonusers among the 262 lung adenocarcinoma cohort." (PMID 32190817, 2020).
breast tumor (23 papers, 2015 to 2025). "The presence of CD163+ macrophages in breast tumor samples has been associated with two times higher risk for disease progression and shorter overall survival." (PMID 40425576, 2025). "Clinically, we found that high numbers of CD163+ M2-macrophages were strongly associated with fast proliferation, poor differentiation, estrogen receptor negativity and histological ductal type (p<0.001) in the studied cohort of human primary breast tumors." (PMID 26243145, 2015). "Next, we investigated the association between CD68, CD163, CD86, and PD-L1 expression and the clinicopathological features of primary breast tumors." (PMID 40510346, 2025). "To further evaluate the clinical relevance of IL1α expression and macrophage infiltration in patients with TNBC, we used IHC staining to compare the levels of IL1α and CD163 between normal breast tissues and breast tumors." (PMID 37551997, 2023). "In this study, CD163 expression and polarization of the M1 and M2 macrophages and cytokines released in culture supernatant in the presence of melatonin and breast tumor cells were evaluated in colostrum." (PMID 37569777, 2023). "Our studies also revealed that S100A7 and cPLA2 are positively correlated with the infiltration of CD163+ M2-TAMs in invasive breast tumor tissues." (PMID 35135586, 2022). "In this study, we evaluated the frequencies of FoxP3+ and CD163+ cells in the TC and IM in primary breast tumors and found an accumulation in either of these areas which was associated with increased densities of CD8+ cells." (PMID 36551693, 2022). "In our recent study, we showed that high frequencies of CD163+ cells combined with low frequencies of CD8+ cells in the center of breast tumors represents a significant biomarker for poor prognosis." (PMID 36551693, 2022). "For further differentiation, we stained FFPE tissue sections from primary human breast tumors of our patient cohort with pan‐cytokeratin for tumor cells, αSMA to identify fibroblasts, and CD163, CD68, and CD206 to mark macrophages." (PMID 33377644, 2020). "Macrophage infiltration (CD68) and activation status (HLA-DRIIα, CD163) were evaluated in a large cohort of human primary breast tumors (562 tissue microarray samples), by immunohistochemistry and scored by automated image analysis algorithms." (PMID 26243145, 2015). "CD163 expression was evaluated in breast tumor samples material from 127 women by immunohistochemistry." (PMID 26585897, 2015). "Triple-negative/basal-like breast tumor stroma had more CD163+ and CD68+ cells and a higher proportion of CD163 relative to CD68 when compared to the stroma of luminal A tumors." (PMID 26243145, 2015). "Patients with breast tumors expressing CD163 in >25 % of cancer cells had significantly shorter survival time than patients with tumors expressing CD163 in <25 % of cancer cells, which was also reported on in an earlier study." (PMID 26585897, 2015). "Several clinicopathological studies reported CD163 expression by cancer cells in breast tumors, colorectal, and urinary bladder cancers." (PMID 26585897, 2015). "Next, we analyzed the impact of CD68, CD163, CD86, and PD-L1 expression on recurrence-free survival (RFS), defined as the time between the initial diagnosis of the primary breast tumor and cerebral progression." (PMID 40510346, 2025). "Of these, 262 women (training cohort) had breast tumor IHC for four classic immune cell markers (CD8, CD4, CD20, and CD163)." (PMID 36376974, 2022). "We detected higher numbers of CD163+ than CD8+ cells in both tumor regions, consistent with the increased influx of TAMs in breast tumors." (PMID 28428887, 2017). "While mRNA encoding the myeloid cell marker CD11b (ITGAM) was expressed at equal levels in all breast tumour subgroups, mRNA of the anti-inflammatory markers CD163 and S100A9 were expressed at significantly higher levels in basal than luminal A breast tumours." (PMID 27725631, 2016).
breast tumor (continued). "(F) Analysis of CD163 expression levels between primary breast tumors of patients with and without metastases." (PMID 39513934, 2024). "The results indicated that the protein levels of IL-10, CD163, and VSIG4 were significantly increased in breast tumor tissues in mice overexpressing HPSE, indicating that HPSE might promote macrophage M2 polarization (CD163, VSIG4) by upregulating IL-10." (PMID 34461608, 2021). "We used breast tumor tissues from each patient to make tissue microarrays that were then stained for leukocyte and myeloid markers including CD4, CD8, CD20, CD25, CD68, and CD163 using immunohistochemical techniques." (PMID 28794686, 2017). "In this study, we demonstrate that co-transplanted primary human monocytes differentiate into CD163+ myeloid cells, both in luminal A and TN breast tumour grafts, but that the immunosuppressive MDSC-marker S100A9 (refs 37, 38) was expressed only by the CD163+ cells in the TN grafts." (PMID 27725631, 2016). "In this study CD163+ cells in primary breast tumor tissue were brought up as a negative prognosis factor for RFS." (PMID 26243145, 2015). "However, using scRNASeq data from breast tumors, we mainly observed an expression of CMKLR1 in a subset of TAM C1QC+ that expressed usual M2 signature, including high expression of CD14 and CD163, whereas CMKLR1 expression was low in a subset of TAM ISG15+ that expressed classical M1 signature." (PMID 37539056, 2023). "In addition, in breast tumors with adipose tissue-rich stroma, the number of CD163+ macrophages was greater with stromal ATX positivity, and the numbers of CD68-positive and CD163-positive macrophages were greater in cases with stromal LPA3 receptor positivity." (PMID 32824846, 2020). "(E) Analysis of the staining of H&E, CD163 (brown), FABP4 (red) in primary breast tumors of patients with and without metastasis." (PMID 39513934, 2024).
hepatocellular carcinoma (22 papers, 2013 to 2024). A malignant tumor that arises from hepatocytes. "This is consistent with studies of other types of cancer that have found that increased infiltration of CD163-expressing cells is associated with shorter OS in follicular lymphoma, triple-negative breast cancer, and hepatocellular carcinoma." (PMID 36765852, 2023). "This is in keeping with studies which found that increased infiltration of CD163 was associated with poorer OS in hepatocellular carcinoma, triple negative breast cancer and follicular lymphoma." (PMID 33481339, 2021). "In hepatocellular carcinoma, an increase in M1 macrophages associated with increased time until recurrence, and a reduced CD163/CD68 ratio was correlated with a worse outcome, which corroborates, at least partially, our results." (PMID 31481956, 2019). "Our results support the previous researches that the infiltration of CD163-positive macrophages associated with poor prognosis in various tumors, such as hepatocellular carcinoma, renal cell carcinoma and bladder cancer." (PMID 26769084, 2016). "In vitro, HGF and IGF secreted by CD163+ macrophages were sufficient to induce hepatoma cell proliferation." (PMID 36845555, 2023). "Investigations have shown CD163 (M2 macrophage class B scavenger receptor), as a biomarker for macrophage activation in lung, breast and hepatocellular carcinoma." (PMID 37397243, 2023). "We have previously reported similar findings in hepatocellular carcinoma, in which PD‐L1 expression was correlated with infiltration of CD163+ cells." (PMID 28602029, 2017). "Due to observations that M2-like CD163+ TAMs were associated with poor prognosis in HNSCC, breast, gastric, colorectal and hepatocellular cancers, this study investigated whether CD163+ TAMs could also be adopted as a prognostic indicator in OSCC." (PMID 37397243, 2023). "Expression of dynamin-related protein 1 (Drp1), the most important protein for mitochondrial division, showed a significant positive correlation with the percentage of CD163+ cells in hepatocellular carcinoma (HCC)." (PMID 39199574, 2024). "Similar to findings of M2-like CD163+ TAMs, the presence of CD68+ TAMs is associated with poor prognosis in nasopharyngeal carcinoma (NPC), gastric and hepatocellular cancers, this study investigated whether CD68+ TAMs could also be adopted as a prognostic indicator in OSCC." (PMID 37397243, 2023). "In hepatocellular carcinoma, there is a positive correlation between CXCL6 and CD163 expression in patient samples, and TAMs promote cancer cell proliferation and migration by activating CXCR2/IFN-g/p38 MAPK/NF-κB signaling." (PMID 39199574, 2024). "Another study further reported that M-CSF density and the CD163 and CD31 indices in peritumoral tissues were predictable factors for time to recurrence, DFS and OS in patients with HCC, while M-CSF was involved in the progression of hepatocellular carcinoma after curative resection." (PMID 35008390, 2022). "For example, the high proportion of CD163+ tumor infiltrated macrophages is related to the poor clinical prognosis in clear cell renal cell carcinoma (RCC), which is supported by another report where the decrease of macrophages partially inhibited the growth of hepatocellular carcinoma (HCC)." (PMID 36311793, 2022).